CDH5 (cadherin 5)
Diseases named in the same sentence as CDH5 in open-access papers (continued):
Sharing a sentence is not in itself a finding about the gene and the disease.
breast carcinoma (continued). "When the results from patients with ER-positive tumours with vascular invasion were considered, the CDH5:HPA ratio was able to further discriminate between NSR and REC breast cancer patients." (PMID 27010749, 2016). "Here, we identify CDH5, HOXD1, and HOXD10 as putative STARD13 ceRNAs and they display concordant patterns with STARD13 in different metastatic potential breast cancer cell lines and tissues." (PMID 26985770, 2016). "Knockdown of TACC3 upregulates the expression of Notch4 and CDH5, suggesting that TACC3 may be closely related to Notch4 and CDH5 signaling pathways in breast cancer." (PMID 34149795, 2021). "To investigate whether STARD13-correlated ceRNA network is involved in breast CSC formation, we first detected the expression levels of STARD13, CDH5, HOXD1, and HOXD10 in a pool of CSCs naturally arising within breast cancer cells." (PMID 29848346, 2018). "This promotes us to explore the functions of STARD13-, CDH5-, HOXD1-, and HOXD10-3’UTRs in breast cancer metastasis and whether they possess the functions through acting as ceRNAs." (PMID 26985770, 2016). "In sum, these data testify our hypothesis that STARD13, CDH5, HOXD1, and HOXD10 may bind with miR-9, miR-10b and miR-125b to suppress breast cancer metastasis." (PMID 26985770, 2016). "Moreover, induction of CDH5 during epithelial mesenchymal transformation accentuates breast cancer progression via TGF-β signaling, indicating that in certain tumor cells, CDH5 can induce cellular responses that counteract its inhibitory role in cell–cell contact growth in EC." (PMID 36899372, 2023). "On examination, ER status (P=0.024), CDH5:HPA ratio (P=0.030) and vascular invasion (P=0.038) were all statistically significant suggesting that the CDH5:HPA ratio is of greatest utility as a predictor of breast cancer metastasis in ER positive tumours that have vascular invasion." (PMID 27010749, 2016). "Our recent work has confirmed that STARD13, CDH5, HOXD1, and HOXD10 could co-regulate each other through competing for several shared miRNA binding sites, and thus formed a ceRNA network to coordinately inhibit breast cancer EMT and metastasis, which is denoted as STARD13-correlated ceRNA network." (PMID 29848346, 2018). "The data from ELISAs suggests that CDH5 and CDH5:HPA ratio values may offer a lead time in the diagnosis of metastatic disease, as the average time to metastasis (from diagnosis) in this cohort of patients was 32.0 months (±3 months) post primary breast cancer diagnosis." (PMID 27010749, 2016). "Given the crucial role of STARD13-, CDH5-, HOXD1-, and HOXD10-3’UTRs in breast cancer metastasis, we believe that STARD13-, CDH5-, HOXD1-, and HOXD10-3’UTRs could be therapeutic targets for the development of anti-metastatic strategy for breast cancer treatment in the near future." (PMID 26985770, 2016). "In the lower tertile of CDH5:HPA ratios, 92% of patients with ER-positive primary tumours containing vascular invasion had no sign of distant metastasis, indicating the sub-group of breast cancer patients for whom measurement of this biomarker is the most beneficial." (PMID 27010749, 2016).
endothelial dysfunction (63 papers, 2009 to 2026). In vascular diseases, endothelial dysfunction is a systemic pathological state of the endothelium (the inner lining of blood vessels) and can be broadly defined as an imbalance between vasodilating and vasoconstricting substances produced by (or acting on) the endothelium. "The current study suggests that upregulation of CDH5 expression is associated with neovascularization, whereas downregulation of CDH5 is closely linked to endothelial dysfunction." (PMID 41602344, 2026). "The second network proposed the interaction of beta-catenin with CDH5 and TGFBR1 through Smad molecules to contribute to endothelial dysfunction, often a precursor of CVD." (PMID 24465431, 2014). "(d) Lastly, from our fourth network we have inferred that the interaction of β-catenin with CDH5 and TGFBR1 through Smad molecules could contribute to endothelial dysfunction." (PMID 19997558, 2009). "Overall, cadherin-5 and sTie-2, together with increases in P-selectin, ICAM3, ANGPT1 and PAI-1, suggest that hypoglycemia may result in a shift from endothelial stability to an inflammatory, pro-adhesive and pro-thrombotic phenotype, indicating worsening endothelial dysfunction after baseline." (PMID 41596469, 2026).
Sepsis (52 papers, 2012 to 2026). Sepsis is defined as life-threatening organ dysfunction caused by a dysregulated host response to infection. "Shedding of CDH5 into the circulation is associated with severe acute kidney injury and with more severe organ dysfunction in patients with sepsis and increased levels of soluble CDH5 were associated with poor outcome in severe sepsis." (PMID 31936828, 2020).
atherosclerosis (44 papers, 2011 to 2026). A disease characterized by the build-up of fatty material and calcium deposition in the arterial wall resulting in partial or complete occlusion of the arterial lumen. "The direct inhibition of CDH5 following ETS1 inhibition led to the predicted activation of SHC1-induced atherosclerosis in this model." (PMID 39125657, 2024). "To further confirm the role of endothelial 12/15-LOX, we established EC-specific 12/15-LOX knockdown mice through AAV-shRNA controlled by an EC-specific Cdh5 promoter, which also exhibited a significant alleviation of disturbed flow-induced atherosclerosis after EC-specific 12/15-LOX knockdown." (PMID 40660143, 2025). "Ddr1WT (Ddr1flox/flox, Cdh5-CreERT2−) and Ddr1iECKO mice were injected once with adeno-associated-virus-8 (AAV8)-overexpressing PCSK9 (AAV8-PCSK9) via the tail vein and fed on a Western diet to induce hyperlipidemia, a potent risk factor for atherosclerosis." (PMID 37833282, 2023). "Moreover, DF-induced arterial wall thickening and atherosclerosis in the ligated LCA were significantly reduced in CDH5-Cas9/sgRNA-Txndc5 nanoparticle–treated ApoE−/− mice, compared to those receiving control nanoparticles." (PMID 35061532, 2022). "Moreover, nanoparticles formulated to deliver Txndc5-targeting CRISPR-Cas9 plasmids driven by an endothelium-specific promoter (CDH5) significantly increase eNOS protein and reduce atherosclerosis in ApoE−/− mice." (PMID 35061532, 2022). "CDH1 and CDH5 expressions are increased by C. pneumoniae infection of human brain microvascular endothelial cells, contributing to vascular permeability changes and atherosclerosis." (PMID 22254144, 2011). "We used the endothelial marker gene CDH5 to identify a cluster of endothelial cells and confirmed that these cells express DHX38, MAT2A, CCDC92, FES and FURIN, prompting future efforts to dissect the role of these genes in this cell type in atherosclerosis." (PMID 36928188, 2023). "A combination of markers such as VCAM-1 and cadherin-5 and LUM and ECM-1 in synovial fluid of RA patients could potentially reflect progression of RA with a corresponding increase in atherosclerosis." (PMID 24010407, 2013). "Endothelial-specific KO of HDAC9 with Cdh5-Cre showed reduced plaque area and plaque lipid content, and increased fibrous cap thickness in an atherosclerosis model, suggesting that targeting HDAC9 may aid in the treatment of atherosclerosis." (PMID 38983721, 2024). "To investigate the biological significance of our findings, we generated the inducible EC-specific Ddr1 knockout mice Ddr1iECKO (Ddr1flox/flox, Cdh5-CreERT2+) and employed the mice to test the role of endothelial DDR1 in disturbed flow-accelerated vascular inflammation and atherosclerosis." (PMID 37833282, 2023). "To study the role of endothelial Dicer in atherosclerosis, we generated Apoe−/− mice containing a loxP site-flanked Dicer sequence (Dicerflox) and a transgene with Tamoxifen (TMX) inducible Cre recombinase under control of the EC-specific VE-cadherin (Cdh5) promoter." (PMID 26837267, 2016).
glioma (36 papers, 2013 to 2025). A benign or malignant brain and spinal cord tumor that arises from glial cells (astrocytes, oligodendrocytes, ependymal cells). "It has been reported that CDH5 and erythropoietin-producing human hepatocellular receptor A2 (EphA2) are highly expressed in VM-positive glioma compared with VM-negative glioma, and their expression is required for VM formation." (PMID 36294763, 2022). "In glioma, CDH5 overexpression contributed to the vasculogenic mimicry of glioblastoma stem-like cells and was found to be an independent adverse prognostic predictor for glioblastoma multiforme patients." (PMID 34917508, 2021). "The putative roles for VE-cadherin and EphA2 in regulating the glioma microenvironment are discussed in further detail below (section The VE-cadherin (CDH5) and EphA2 pathways)." (PMID 26085929, 2015). "In our adaptation of this model, spheroids of syngenic C57Bl6 mouse CT2A and GL261 glioma cells modified to stably express blue fluorescent protein TagBFP were engrafted in the endothelial‐specific Pdgfb‐iCre line and in Cdh5‐iCre crossed with the ROSAmT/mG reporter mouse." (PMID 29038312, 2017). "VE-cadherin, also known as CDH5 or CD144, is another key protein commonly upregulated VM-related cells in GBM, particularly in glioma stem-like cells, where it facilitates tumour vascularisation and microenvironment remodelling." (PMID 40869298, 2025). "This compound exerts an inhibitory effect on VM through the downregulation of CDH5, α-SMA, and Akt and VEGFR-2 phosphorylation in glioma cell lines and orthotopic A172 GBM mouse models." (PMID 36294763, 2022). "We analyzed AngioMatrix expression in independent glioma datasets and observed again a significant correlation between AngioMatrix expression and the EC markers PECAM1 and CDH5." (PMID 25301723, 2014). "Furthermore, we tested two EC lineage tracing systems, based on Tie2-Cre/Rosa-LSL-tdTomato and Cdh5-CreERT2/Rosa-LSL-tdTomato, to visualize EC-originated cells in a native glioma microenvironment." (PMID 30150753, 2018). "Pre-treatment with C646 significantly reduced the enrichment of genomic sites in CDH5 and ANGPT1, but not the housekeeping gene RPL30 in radiated cells, thus confirming that P300 HAT activity is essential for radiation stress-induced epigenetic rewiring in glioma cells." (PMID 36261421, 2022).
diabetes (33 papers, 2009 to 2026). "Therefore, we propose that the association of CDH5 with β-catenin might play a significant role in diabetes mellitus through the impairment of vascular endothelial cell function." (PMID 19997558, 2009). "In conclusion, this study provides support for a role for intraocular pressure and diabetes in POAG, suggests a protective effect for adiposity and highlights potential causal roles for serum cadherin 5 and angiopoietin-1 receptor." (PMID 37340071, 2023). "Decreased VE-cadherin (cadherin-5) has been reported in a human diabetic retina, with normal distribution of tight junction proteins ZO-1 and occludin." (PMID 32414036, 2020). "A common trend across the sub-network Wnt_VascularComplication describes the significance of oxidative stress modulating Wnt/β-catenin and CDH5 in diabetes." (PMID 19997558, 2009). "It has been shown that the up-regulation of CDH5 acts as an indicator of coronary artery disease in patients with diabetes mellitus." (PMID 19997558, 2009). "Therefore, it is the first instance, where CDH5 and Wnt are predicted to interact and subsequently lead to vascular complications in diabetes." (PMID 19997558, 2009). "The interactions of β-catenin with CDH5 and TGFBRI have been noted from exclusively diabetes mellitus dataset and also from diabetic nephropathy dataset." (PMID 19997558, 2009).
COVID-19 (26 papers, 2021 to 2025). A disease caused by infection with severe acute respiratory syndrome coronavirus 2. "CDH5, another hub gene, is an important hub gene in high-risk individuals for COVID-19 and LC." (PMID 36199786, 2022). "Indeed, pulmonary edema and capillarostasis are the most commonly observable microscopic changes in COVID-19, and CDH5 (encoding for VE-cadherin) is among the downregulated genes in COVID-19." (PMID 33604758, 2021).
glioblastoma (24 papers, 2012 to 2025). The most malignant astrocytic tumor (WHO grade IV). "A current study demonstrated that Cadherin (CDH5) is expressed in glioblastoma cells and induces vasculogenic mimicry under hypoxic conditions." (PMID 38580922, 2024). "The transcriptomic analysis also revealed that GZ17-6.02 treatment results in suppression of several genes implicated in glioblastoma growth and invasion, such as EGR1, ASCL1, CD109, ABCG2, and CDH5." (PMID 35456993, 2022). "CDH5 is also overexpressed in brain gliomas, correlates with tumor grades, and is an independent adverse prognostic predictor for glioblastoma multiforme patients." (PMID 27362942, 2016). "In glioblastoma, glioblastoma stem like cells (GSCs) that express endothelial cell marker CDH5." (PMID 32169087, 2020). "Moreover, the specific expression of VE-Cadherin (CDH5) in glioblastoma stem cells may contribute to vasculogenesis, especially under hypoxia where VE-Cadherin gene expression is upregulated, when hypoxia-inducible factor-1 or -2 (HIF-1 or -2) bind to and transactivate a VE-Cadherin promoter." (PMID 33036204, 2020). "Spearman correlations did not confirm the influence of G721-0928 on CDH5 mRNA lveelsin glioblastoma cells (R=-0.013, p = 0.96) and spheroids (R=-0.36, p = 0.14)." (PMID 39607670, 2025). "CAFs were also noted to be in close proximity to cells expressing glioblastoma stem cell (GSC) marker CD44 and were enriched in the perivascular niche where GSCs reside based on their proximity to endothelial cells expressing CD34 or CDH5." (PMID 36856115, 2023). "In addition, cadherin-5, VEGF, IGFBP2, and MMP2 (MMP2 was detected in two glioblastoma cyst fluid samples are involved in the generation of vasculogenic mimicry in glioblastomas." (PMID 35659255, 2022).
lung carcinoma (18 papers, 2007 to 2025). "In NSCLC, the increased expression of CDH5 was associated with increased angiogenesis in lung cancer cells, promoting the migration and invasion of lung cancer cells." (PMID 34917508, 2021). "In summary, our study shows that exon 19 deletion mutant EGFR gene is associated with an increased expression of CDH5 in lung cancer cells through increased phosphorylation of EGFR and Akt pathways." (PMID 27362942, 2016). "Further RT-PCR analysis also showed an increased expression of CDH5 mRNA in lung cancer cells with EGFR mutations." (PMID 27362942, 2016). "The association of EGFR mutations and CDH5 expression was studied in lung cancer cells using western blot analysis." (PMID 27362942, 2016). "Significantly upregulated CDH5 was observed in lung cancer cells which were transfected with exon 19 deletion mutation in our study." (PMID 27362942, 2016). "The expression of VEGF and CDH5 in circulation microvesicles has been reported to be associated with distant metastasis in lung cancer." (PMID 27362942, 2016). "CDH5 siRNA was then used to knock down the expression of CDH5 in PC9 lung cancer cells which has exon 19 deletion mutation." (PMID 27362942, 2016). "Our results showed that exon 19 deletion mutation was related to increased angiogenic ability in lung cancer cells, which was at least partially related to increased expression of CDH5." (PMID 27362942, 2016). "In our study, we also observed that the increased expression of CDH5 was associated with EGFR mutations in lung cancer cells." (PMID 27362942, 2016). "We observed that exon 19 deletion mutation was associated with upregulation of CDH5 in vitro and in vivo and higher angiogenic ability in the lung cancer cells studied, and the results support the finding that exon 19 deletion and exon 21 L858R mutation have distinct features." (PMID 27362942, 2016). "In addition, exon 19 deletion mutation of the EGFR gene was associated with increased angiogenic ability in lung cancer cells, which was inhibited by a knockdown of CDH5 siRNA." (PMID 27362942, 2016). "Our study may help to elucidate the association of EGFR mutations and CDH5 with angiogenesis and metastasis in lung cancer cells." (PMID 27362942, 2016). "Increased expression CDH5 is observed in lung cancer cells with EGFR mutations." (PMID 27362942, 2016). "Our result may provide an insight into the association of mutant EGFR and CDH5 expression in lung cancer and aid further development of target therapy for NSCLC in the future." (PMID 27362942, 2016). "An increased expression of CDH5 proteins was observed in PC9 and H1975 lung cancer cells with EGFR mutations." (PMID 27362942, 2016). "The mechanism about how CDH5 was regulated by mutant EGFR genes and the association of EGFR mutation with angiogenesis, migration, and invasion of lung cancer cells were further studied." (PMID 27362942, 2016). "After inhibition of the phosphorylation of EGFR, downregulation of CDH5 protein was observed in the lung cancer cells studied." (PMID 27362942, 2016). "In our study, a higher expression of CDH5 was also observed in PC9 lung cancer cells with exon 19 deletion mutation and lung cancer cells transfected with exon 19 deletion mutant EGFR gene." (PMID 27362942, 2016). "In this study, we investigate the correlation between EGFR mutations and cadherin-5 (CDH5), which is an angiogenic factor, in lung cancer cells." (PMID 27362942, 2016). "Immunofluorescent study was used to study the expression of CDH5 protein in lung cancer stable cells." (PMID 27362942, 2016). "A significantly higher expression of CDH5 is observed in exon 19 deletion stable lung cancer cells and mouse xenografts." (PMID 27362942, 2016). "Higher expressions of CDH5 protein and mRNA in lung cancer stable cells transfected with exon 19 deletion EGFR gene compared to wild type EGFR gene transfected stable cells were observed." (PMID 27362942, 2016).